EGR1 (early growth response 1)
Diseases named in the same sentence as EGR1 in open-access papers (continued):
Sharing a sentence is not in itself a finding about the gene and the disease.
cancer (continued). "Among these genes, HMGA2, CLDN1, TFPI2, KIAA0101 and EGR1 are cancer related genes according to Diseases Association Analysis and increased expression of EGR1 was confirmed by further semi-quantitative RT-PCR, quantitative RT-PCR and western blot in BCL6B re-expressed HepG2 and SNU449 cells." (PMID 25909168, 2015). "Reexpression of EGR1 in EGR1-deficient transformed cell lines limits cancer cell growth and tumorigenicity, suggesting a role for EGR1 in promoting the growth arrest of transformed cell variants and it also augments the sensitivity to chemotherapeutic treatments." (PMID 24787739, 2014). "We found that CBX7 negatively or positively regulates the expression of several genes (such as SPP1, SPINK1, STEAP1, and FOS, FOSB, EGR1, respectively) associated to cancer progression, by interacting with their promoter regions and modulating their transcriptional activity." (PMID 24865347, 2014). "Inhibition of Egr-1 by a dominant-negative mutant, or siRNA-mediated knockdown, significantly decreased the expression of the caspase-8 inhibitor protein, c-FLIP, especially its short isoform (c-FLIPS) and Egr-1 expression associated with high c-FLIP expression in a number of cancer cell lines." (PMID 20087343, 2010). "This signaling pathway includes the up‐regulated transcription factors NR4A3 and EGR1/3, which are known regulators of cancer progression, EMT, angiogenesis, and inflammation." (PMID 39739693, 2025). "In the cancer cells of the bladder, EGR1 promoted cell migration, invasion, and gemcitabine resistance by regulating SOX5." (PMID 39866235, 2025). "The EGR1 promoter contains multiple CRE regions, indicating that ATF5 suppresses EGR1 expression in cancer cells on stiff ECMs by binding to CRE." (PMID 40124511, 2025). "In these systems, fusion of pre-engineered DNA nanostructure-loadedliposomes with cells leads to autonomous intracellular assembly ofallosterically ATP-stabilized DNAzymes cleaving the EGR-1 mRNA, resultingin selective apoptosis of cancer cells." (PMID 40403280, 2025). "Secondly, this study identified EGR1 as an anti-metastatic gene in ccRCC cancer cells, showing its ability to inhibit cell migration and invasion." (PMID 39866235, 2025). "Collectively, these results indicated that stiff ECMs activate JAK signaling, leading to the formation of ATF5-MYC complexes in nuclei, thereby preventing EGR1 transcription in cancer cells." (PMID 40124511, 2025). "Conversely, in other cancers, EGR1 can enhance stemness and predict poor outcomes in uterine cervical cancer by promoting SOX9 expression." (PMID 39866235, 2025). "These beneficial effects are complementary to the reported beneficial effects specifically noted with VEGF, NO-system, egr-1 gene, and carcinoma models." (PMID 40573323, 2025). "Currently, little is known of the role of EGR1 in anti-cancer immunity, which presents an opportunity for us to explore this as an immunotherapeutic target in the stipulated cancer types." (PMID 39766097, 2024). "In untreated cancer cells, EGR1 levels remained low despite high ERK signaling from EML4-ALK, consistent with EGR1 adaptation to tonic ERK signals." (PMID 39488530, 2024). "The D132A mutation of AURKA blocks the activation of cleaved caspase 3 and EGR1 expression, reducing the sensitivity of cancer cells to the chemotherapeutic drug Taxol in vitro and in vivo." (PMID 38994036, 2024).
cancer (continued). "High EGR1 expression has been found in a variety of cancers such as gastric, colorectal, hepatocellular, and cervical cancer and has been associated with poorer prognostic outcomes such as distant metastasis and poor survival." (PMID 38408959, 2024). "Mutant of AURKAD132A blocks the expression of cleaved caspase 3 and EGR1, and prevents Taxol-induced apoptosis of cancer cells in vitro." (PMID 38994036, 2024). "Nevertheless, MYC was frequently ranked second in cancer types, with EGR1 as the top-ranking candidate." (PMID 39766097, 2024). "We also explored the expression of the underlying cancer‐promoting genes within cluster 3; these genes included Cdkn1a, Plaur, Ptgs2, Cox17, Lilrb4q, G0s2, Egr1, and Cxcl2, with previous reports suggesting their implication in increasing cancer progression." (PMID 39113226, 2024). "The EGR1 promotes cancer cell EMT by initiating the transcription of E-cadherin transcriptional inhibitors (i.e., SNAIL and SLUG), thereby promoting the invasive and metastatic properties of cancer cells." (PMID 38944814, 2024). "In order to explore the potential impact of EGR1 downregulation on the efficacy of sorafenib in HCC, we utilized the genomics of drug sensitivity in cancer (GDSC) database to predict IC50 values of sorafenib based on EGR1 expression." (PMID 38287371, 2024). "In both cell lines and samples from patients with cancer, the fusion protein and EGR1 bound to EGR1-targeted promoters and enhancers, increasing their accessibility and expression of the corresponding genes." (PMID 39370970, 2024). "Recently, it was shown that components of the AP-1 transcription factor (FOS, FOSB, JUN), EGR1, and NR4A1 behave as a conserved co-regulated group of genes whose expression is associated with ZFP36 in cancer cells." (PMID 39026155, 2024). "Previous studies have determined a direct role for the SS18-SSX fusion protein in regulating expression of several cancer-related genes, such as EGR1, FOS, IGF2, FZD10, SOX2, UNCX and CDH4." (PMID 39045458, 2024). "Heparanase (HPSE) is a cancer metastasis protein that is regulated by the hnRNPU/p300/EGR1/HPSE axis, promotes high expression of HPSE enhancer RNA, is an independent prognostic factor for poor prognosis in cancer patients." (PMID 37091789, 2023). "Previous works identified EGR1 as a target gene getting promptly activated by various mitogens, and apoptotic signaling pathways in various cancers including lung, prostate, and breast." (PMID 37958905, 2023). "Mechanistically, METTL3 serves as the m6A transferase of EGR1 mRNA, leading to its stabilization and activation of the EGR1/Snail regulatory loop, resulting in cancer cell metastasis." (PMID 37015927, 2023). "Our findings demonstrate that EGR1 plays a crucial role in facilitating VM in aggressive cancer cells by regulating KLF4 expression." (PMID 37762678, 2023). "c-Jun, c-Fos, NFКB, JunB, EGR-1 and FosB by qRT-PCR after treating PBMCs with cfChPs (10ng) isolated from sera of cancer patients." (PMID 38274821, 2023). "Wound healing assay was also performed to verify the migration ability of cancer cells after knockdown or overexpression of EGR1." (PMID 36932397, 2023). "From the perspective of interpreting VM as the differentiation of cancer stem cells into endothelial-like cells, it can be inferred that EGR1 maintains the stemness and endothelial differentiation capacity of cancer stem cells by regulating KLF4." (PMID 37762678, 2023). "Our particular focus was on comprehending the MAPK-dependent activation of EGR1 in driving transcriptional regulation and subsequently controlling cell proliferation and growth in cancer cells." (PMID 37958905, 2023). "Corepressors NAB1/2 (NGFI-A binding protein) interact with and repress EGR1 (also called NGFI-A/zif268), which play an important role in various cancer development." (PMID 36979412, 2023).
cancer (continued). "We uncovered a Hippo regulon in neutrophils with unique YAP signature genes (e.g., ICAM1, CD14, EGR1) distinct from those identified in epithelial and/or cancer cells." (PMID 36921037, 2023). "The significance of the EGR1 protein as the downstream regulator of the MAPK signaling pathway gains higher importance as it can be targeted for cancer therapy." (PMID 37958905, 2023). "Together, these data indicate that Trametinib affects the proliferation of BHD patient-derived cancer cells by acting on the EGR1-TFEB axis." (PMID 36888606, 2023). "NAB2–STAT6 fusions have been shown to function as transcriptional activators and upregulate the expression of cancer-promoting EGR1 target genes including FGFR1 and NTRK1, as well as IGF genes in SFT patient samples." (PMID 37370737, 2023). "Since EGR1 plays a positive role in cancer cell development, EGR1 can be applied to anticancer research in the future." (PMID 35563324, 2022). "Together, these results suggest that patients with different cancers can take some medicines or natural compounds to induce EGR-1 expression before chemotherapy to promote cancer cell sensitivity to medication." (PMID 36233659, 2022). "After the EGR-1 gene knockdown, the initial outcome showed an effective gene knockdown in different cancer cell lines, including CE48T and CE81T." (PMID 36233659, 2022). "Phosphatase and tensin homolog (PTEN), a proapoptotic factor that is altered in numerous cancers, is also directly regulated by EGR1." (PMID 36338037, 2022). "EGR1 codes for a transcription factor involved in healing, fibrosis, and immune responses, that has recently gained recognition for its role in cancer progression." (PMID 35456993, 2022). "Based on our clinical investigation and in vitro study, we believe that EGR-1 plays a double-edged sword role in cancer development." (PMID 36233659, 2022). "By dissecting diverse cell types comprising the TME, we identified a novel subset of cancer-associated fibroblast, which showed enriched epidermal growth factor receptor (EGFR)-related transcripts including early growth response 1 and 2 (EGR1 and EGR2)." (PMID 35464471, 2022). "A previous study demonstrated that EGR1 is related to cancer therapy resistance, such as radiation resistance and drug resistance." (PMID 35812443, 2022). "The results in CpG-rich hyper-methylated DMRs consistently identified CpG-rich low complexity motifs such as EGR1 or KLF motifs in most cancer types." (PMID 35331302, 2022). "Some results of the previous papers are contrary to ours, indicating that EGR-1 is an oncogene in many types of cancer." (PMID 36233659, 2022). "Synergizing these studies, we zeroed in on a pan-cancer regulatory axis comprising EGR1-MALAT1-driver coding genes playing a role." (PMID 35534592, 2022). "In cancer, Egr-1 can act as a tumor suppressor by promoting apoptosis in response to stress and DNA damage." (PMID 35806184, 2022). "Hyper-methylated CpG-rich DMRs were consistently enriched in G + C-rich low complexity motifs such as EGR1 or KLF in most cancer types." (PMID 35331302, 2022). "EGR1 has been reported to be involved in the regulation of cell growth, differentiation, and apoptosis in several cancer types." (PMID 33564067, 2021). "EGR1 belongs to the EGR family and has been implicated in the regulation of cancer cell growth, metastasis and apoptosis." (PMID 34346162, 2021). "A previous study showed that the transcription factor Elk-1 is a downstream target of Erk1/2 MAP kinases, regulating the migration of many types of cancer via its downstream targets including c-fos, EGR1, and PKCα." (PMID 34488769, 2021). "Of note, data derived from TCGA showed that the expression of EGR1 significantly correlated with the treatment outcomes in cisplatin-treated cancer patients." (PMID 34268111, 2021). "Our results showed a high EGR1 immunoreactivity in the nuclei of adjacent normal cells compared with cancer cells." (PMID 34497759, 2021).
cancer (continued). "Research on the mechanism of action of EGR1 in cancer is expected to point to a new cancer treatment strategy and/or a new marker for theranostics." (PMID 33842351, 2021). "An increasing number of reports suggest that decreased expression of EGR1 is involved in cancer progression." (PMID 34235076, 2021). "A recent study also reported that ATF3 and EGR1 are involved at the beginning of the inflammatory processes related to cancer." (PMID 34497759, 2021). "EGR1 is a key gene involved in regulating cell proliferation and apoptosis in a variety of cancer tissues, and knockdown of EGR1 has been shown to promote resistance to cisplatin." (PMID 34268111, 2021). "Many types of cancer cells secrete extracellular vesicles, which are known to stimulate the migration of vascular endothelial cells by upregulating EGR1." (PMID 33842351, 2021). "We also observed the splicing switch from cancer-specific isoform to normal isoform in EGR1 depleted cells." (PMID 34616729, 2021). "EGR1 has been found to play a role in promoting apoptosis or inhibiting growth in many cancer studies." (PMID 33461495, 2021). "Although a crowd of studies elucidate the mechanism of four members of the EGR family for plentiful types of cancers, the landscape of the prognostic value and role of EGR1 are poorly explored in BRCA." (PMID 34178038, 2021). "Early growth response family members (EGRs), EGR1–4, have increasingly attracted attention in multiple cancers." (PMID 34178038, 2021). "For the sake of understanding a pan-cancer view of EGRs’ expression, the mRNA expression levels of EGR1–4 on the Oncomine were analyzed." (PMID 34178038, 2021). "Determining and exploiting the involvement of EGR1 in cancer will help develop new therapies for patients with malignant tumors." (PMID 33842351, 2021). "Combining NPG with HO-1 inhibitor demonstrated down-regulation of genes involved in cancer cell invasion and proliferation (EGR1, CXCL2, AREG, CXCL3, EREG, CD3e, CD3g, CD74, and B2M) as compared to NPG or to control animals." (PMID 34066839, 2021). "In this study, clinic tissue analysis showed a downregulation of EGR1 expression in cancer tissues compared with the normal tissue." (PMID 34497759, 2021). "In eight pairs of fresh cancer and adjacent normal tissues from clinical NSCLC patients, we found the reduction of EGR1 expression in cancer tissues." (PMID 34497759, 2021). "Other studies also reported that GDF15 contributes to cancer cell apoptosis due to the upregulation of EGR1 as a critical antitumorigenesis role." (PMID 34681812, 2021). "Among these upregulated genes, we focused on EGR1, since it has multiple functions relating to the development of cancer, cardiovascular disease, memory and psychiatric disorders, and apoptosis." (PMID 33294641, 2020). "In the cancer tissues analyzed, the staining observed for expression of both EGR1 and PRR11 protein nearly overlapped in the same regions, indicating a consistent expression pattern between these two markers." (PMID 33276775, 2020). "EGR-1 is a downstream transcription factor of HOPX that controls cancer progression through induction of IGF-II, PDGF, and TGF-β." (PMID 31934721, 2020). "EGR1 overexpression vector and miR‐23b‐3p overexpression vector were transfected into sorafenib‐resistant Hep3B cells, respectively, to explore the effects of EGR1 and miR‐23b‐3p on the drug resistance mechanism of cancer cells." (PMID 32324343, 2020). "For example, HPSE eRNA promotes cancer progression by interfering with the chromatin looping and regulating the hnRNPU/p300/EGR1/HPSE axis." (PMID 33392092, 2020). "CUR exerts its effects by downregulating multiple cell signaling pathways, which include NF-κB, STAT3, activated protein-1 (AP-1) and epidermal growth response-1 (Egr-1), which are all crucial in the development and progression of cancer." (PMID 30890933, 2019).
cancer (continued). "To further validate that Oct4 controls cancer metastasis through upregulation of Egr1 in vivo, we performed lentivirus-mediated knockdown of Egr1 in A549-Oct4 and A549-Vector cells." (PMID 31399076, 2019). "The role of Egr1 in cancer cells is complex, which is dependent on the cell types and various stimuli." (PMID 31399076, 2019). "Silencing of Egr1 attenuated radiation-induced apoptosis in normal tissue, while sensitized the two cancer cell lines due to differential response based on the cellular context." (PMID 31367263, 2019). "Elk-1 regulates migration of multiple cancer types through its downstream targets including c-fos, EGR1, and PKCα." (PMID 29765550, 2018). "Based on the results, we found that STAT6, a cancer-related TF, regulated FOS and FOSB, while FOS and EGR1 were coregulated by 2 cancer-related TFs, including BRCA1 and SP1, respectively." (PMID 30228980, 2018). "As EGR1 has been shown to reduce proliferation in other cancer cell types, we assessed RH30 cells stably expressing EGR1 for proliferation and viability and found that the over expression of EGR1 in RH30 cells significantly reduced cell proliferation." (PMID 29719592, 2018). "Studies suggest that Early Growth Response-1 (EGR-1) is a cancer suppressor gene and accordingly, it was found that EGR-1 was significantly upregulated in oleuropein (8-fold, p = 0.018) and hydroxytyrosol (20-fold, p = 0.018) treated MIA PaCa-2 cells." (PMID 30004416, 2018). "We intersected 237 common DEGs and curated 36 cancer-related TF families to get three differentially expressed TFs (EGR1, FOS, and FOSB) in HCC." (PMID 30228980, 2018). "EGR1, one of the immediate-early response genes, can function as a tumor suppressor gene or as an oncogene in cancer." (PMID 29719592, 2018). "A role for EGR1 in regulating cellular metabolic pathways has been reported in several disease models including cancer." (PMID 29228577, 2017). "For example, curcumin, a natural compound, can transitorily induce expression of EGR1 and inhibits cancer cell proliferation." (PMID 29246166, 2017). "Within our gene-metabolite integrated model, we selected to further study the role of EGR1 (early growth response 1), a gene that is known to be deregulated in some cancers." (PMID 29228577, 2017). "It has also been reported that the latent membrane protein 1 (LMP1) positively regulates Egr-1 through the involvement of NFκB in order to mediate LMP1 dependent cancer cell survival." (PMID 29207655, 2017). "EGR1, a pro-apoptotic protein, inhibits growth and increases apoptosis in human cancer cells by upregulating PTEN." (PMID 27935858, 2017). "Among the targets of EGR1 are many genes that are involved in proliferation and prevention of apoptosis, which gives EGR1 a putative role in the development of cancer." (PMID 28180113, 2017). "In response to oxidative stress, Ref-1 associates with EGR1 in the nucleus to increase PTEN activation, which inhibits cancer growth and ultimately leads to apoptosis." (PMID 27935858, 2017). "The function of EGR1 in cancer pathogenesis is complex because it functions both in-cell proliferation and apoptosis." (PMID 27244890, 2016). "We demonstrated that the potent anti-angiogenic effect of miR-192 stems from its ability to globally downregulate angiogenic pathways in cancer cells through regulating two key transcription factors, EGR1 and HOXB9." (PMID 27041221, 2016). "EGR1 is a pivotal regulator of cell fate and mitogenesis with critical roles in development and cancer." (PMID 26013771, 2015). "EGR1 activates the miR-199a gene locus, which is mainly responsible for the biogenesis of mature miR-199a-5p and -3p in these cancer cell lines." (PMID 25673149, 2015). "Studies about EGR1 have been suggested that it is a cancer suppressor gene and a transcriptional regulator." (PMID 26088082, 2015).